RNU6-452P (RNA, U6 small nuclear 452, pseudogene)
Gene: Small nuclear RNA gene on chromosome 10 (27,335,501 to 27,335,607, reverse strand). Ensembl gene ENSG00000207135.
Homologues: Orthologues: chimpanzee U6 (98% identical), dog U6 (68% identical), rabbit U6 (67% identical), pig U6 (65% identical), rabbit U6 (62% identical). Paralogues in human: RNU6-666P (94% identical), RNU6-1207P (91% identical), RNU6-811P (90% identical), RNU6-1293P (88% identical), RNU6-156P (88% identical), RNU6-1210P (87% identical), RNU6-458P (87% identical), U6 (87% identical), RNU6-1132P (86% identical), RNU6-614P (86% identical), RNU6-721P (85% identical), U6 (85% identical), and 1288 more.